IL10 (interleukin 10)
Diseases named in the same sentence as IL10 in open-access papers (continued):
Sharing a sentence is not in itself a finding about the gene and the disease.
tumor (continued). "This polarization was also confirmed via increasing in the expression level of cytokines such as interferon gamma (IFN-γ) and tumor necrosis factor alpha (TNF-α) which led to a significant reduction in the amount of interleukin 10 (IL-10), an immunosuppressive cytokine that promotes tumor growth." (PMID 35954362, 2022). "In addition, tumor cells can recruit suppressive cells, such as regulatory T cells (Tregs) or suppressive cytokines, including IL10." (PMID 35624717, 2022). "Furthermore, tumor analysis showed that probiotic group therapy reduced IL-10 accumulation in the tumor microenvironment of the treated mice." (PMID 36127698, 2022). "Our group has found within the sequence of nonmutated tumor associated proteins are class II epitopes that can selectively induce either an IFN-γ dominant or IL-10 dominant response." (PMID 35948756, 2022). "Such anti-tumor immunity may be attenuated by cancer cells expressing immunosuppressive cytokines, such as IL-10." (PMID 35216394, 2022). "The study’s results showed that the level of IL-10 in the cerebrospinal fluid correlates positively with the tumor size and may help diagnose the development of lymphoid malignancies." (PMID 36009467, 2022). "IL-10 also promotes the differentiation of tolerogenic DCs (tDCs), tumor-associated macrophages (TAMs), and MDSCs, which invade the TME to promote neovascularization and tumor immune escape." (PMID 35173722, 2022). "Breg cells (CD19+ IL-10+ or CD19+ CD24hiCD38hi) increased the immune regulatory protein of PD-L1 and CTLA4 to promote the regulatory T (Treg) cells, myeloid-derived suppressor cells (MDSC), and tumor-associated macrophages (TAMs)." (PMID 35563678, 2022). "In addition, the researchers also reported that the inhibition of IL-10 enhanced the role of anti-PD-1 antibodies in amplifying tumor-specific CD8+ T cells, thereby enhancing their antitumor activity." (PMID 35681453, 2022). "IL-10 promotes cytotoxicity but inhibits anti-tumor responses." (PMID 36142615, 2022). "Additionally, S1P can also activate HIF-1a, resulting in the production of VEGF and pro-tumour cytokines such as IL10 and IL6." (PMID 36497148, 2022). "Collectively, the present results represent the first time that KCa3.1 activators are a possible target for overcoming IL-10-mediated escape from tumor immune surveillance in the TME, through their inhibition of the IL-10 in TAMs via the ERK-CREB and JNK-c-Jun cascades." (PMID 35955737, 2022). "In contrast, we observed a significant decrease in IL5, IL10, IL13, and IL6 levels, which are typically associated with tumor-promoting type 2 immune responses, which are known to support tumor growth, metastatic dissemination, and tumor evasion of immune surveillance." (PMID 35715953, 2022). "Moreover, intermittent hypoxia in a solid tumor environment induced the upregulation of tumor-evasive factors, such as IL-10, HIF-1α, TGF-β1, and TNF-α." (PMID 36233088, 2022). "Indeed, GBM tends to induce an immunosuppressed TME enriched in immunosuppressive chemokines (eg, TGFβ, IL10, IL6) secreted by tumor cells, microglia and tumor-associated macrophages (TAMs)." (PMID 36212741, 2022). "TAMs are broadly M2 polarized, and IL-10, IL-12p40 and G-CSF all have been shown to play important roles in impacting the tumor microenvironment through regulation of TAMs68–70 which could be targeted by the LLO-SK for cancer bacteriotherapy." (PMID 36042261, 2022). "EZH2 inhibition, either pharmacologically or genetically, destabilizes FOXP3 expression in Treg cells and specifically reprograms tumour- infiltrating Treg cells through driving the expression pro-inflammatory genes (e.g., IL-2) while inhibiting key immunosuppressive genes such as IL-10 and TGF-β." (PMID 36569832, 2022). "The combination of PD-1 and IL-10 blockade significantly reduced tumor burden." (PMID 35663968, 2022).
tumor (continued). "Furthermore, IL-10 was expressed in the cell-culture supernatant of GC TAMs, and that exposing tumor cells to this particular supernatant increased tumor proliferation." (PMID 35884907, 2022). "In contrast, M2 macrophages, which are stimulated by IL-4 and IL-13 (produced by T-helper 2 cells), play a critical role in tumor initiation, proliferation, metastasis, and immune evasion, and express anti-inflammatory elements, such as IL-10 and transforming growth factor (TGF)-β." (PMID 35844605, 2022). "However, B cells can also have regulatory functions, thereby promoting tumor progression through the cytokines IL-10 and TGF- β." (PMID 35326515, 2022). "It is possible that PD-induced reduction in IL-10 in the tumor microenvironment could affect indirectly EGFR, thus preventing downstream activation of Akt and ERK1/2 kinases in malignant cells." (PMID 35955576, 2022). "Moreover, the NP-mediated antigen delivery stimulated the production of immune-stimulating cytokines such as IFN-γ and reduced the production of immune-inhibitory cytokines such as IL-10 compared to the use of soluble tumor cell lysate." (PMID 36338731, 2022). "MM TME is characterized by the presence of several immunosuppressive cellular and non-cellular elements including myeloid-derived suppressor cells (MDSCs), tumor-associated M2-like macrophages, regulatory T-cells, and tumor promoting and immunomodulatory factors such as IL-6, TGF-β, IL-10, PGE2." (PMID 36142133, 2022). "The discrepancy of these results might be due to the difference of tumor microenvironment which modulates the expression and function of IL-10." (PMID 36531027, 2022). "Indeed, this mechanism is due to the activation of Wnt/beta-catenin signaling, which results in elevating immune-regulatory molecules expression, particularly IL-10 in the tumor microenvironment dendritic cells." (PMID 36437782, 2022). "Additionally, anti-IL10 antibody partially blocked proliferation induced by the supernatant, supporting a link between IL-10 and tumor proliferation." (PMID 35884907, 2022). "Interestingly, culture media from tumour-associated NK cells induced THP-1 monocyte cell lines to express TAM-related genes (i.e., Arg1, CXCL8, IL-10)." (PMID 35565201, 2022). "Thus, in most likelihood, the observed IL-10 expression in fresh-frozen GBM tumors indicates the infiltrated immune cells such as MDSCs in the tumor microenvironment." (PMID 35720420, 2022). "As IL-10, increased TGFβ production by MDSCs has been reported in various tumor types." (PMID 35757002, 2022). "Dysfunctional interaction of tumor and stromal cellular components leads to a predominantly anti-inflammatory cytokine profile with interleukin-10 (IL-10), transforming growth factor (TGF)-beta and other cytokines, produced by immunosuppressive cells, for example, regulatory T cells (Tregs)." (PMID 35495634, 2022). "The tumor-stimulated immunosuppression is favored by producing the checkpoint receptor ligands accompanied by the secretion of anti-inflammatory cytokines such as IL-10 and TGF-β by the tumor cells." (PMID 36510217, 2022). "Similarly, IFN-γ promotes polarization of macrophages to M1 anti-tumor phenotype, while the presence of cytokines, such as interleukin (IL)-4, IL-10 and IL-13 stimulate M2 TAMs with pro-tumor phenotype." (PMID 35268568, 2022). "Complementarily, locally produced IL-10 has an inhibitory effect on T-helper (Th) cells, monocytes, macrophages, and dendritic cells (DC), resulting in an immune tolerance condition that favors tumor growth." (PMID 35741603, 2022). "M2 macrophages are involved in tumour progression and invasion, as they are mainly identified in early inflammatory infiltrate, being stimulated by Th2 cells and anti-inflammatory stimuli (IL-4, IL-10, IL-13, or monocyte colony-stimulating factor—M-CSF)." (PMID 35334544, 2022).
tumor (continued). "TAMs may be activated classically (known as the M1 type) by IFN-γ and TNF to suppress tumor progression, or alternatively (known as the M2 type) by IL-4 and IL-10 to promote tumor immune evasion in different conditions." (PMID 36230570, 2022). "Tumor-infiltrating PD-1+ myeloid cells exhibited immunosuppressive phenotypes with upregulated of PD-L1 and IL-10 and could directly inhibit anti-tumor T-cells infiltration or effects via the PD-1/PD-L1 axis." (PMID 35663968, 2022). "Indeed, immunosuppressive signals released by tumor cells or immunomodulatory cells, such as prostaglandin E2/cyclooxygenase-2, IL-10, TGF-β or vascular endothelial growth factor (VEGF), can induce DC dysfunctionality." (PMID 36189323, 2022). "Macrophages in the primary tumor TME can synthesize IL10, another Th2 cytokine." (PMID 36077870, 2022). "On the other hand, it was demonstrated that along with the metastasis of the tumor cells into the draining LNs and progression of the disease to advanced stages, the frequencies of CD8+ T cells expressing Tc2-associated cytokines (IL-4, IL-10) increased." (PMID 36376825, 2022). "Interestingly, the six ALCL patients with upregulated PDGFRB expression also showed a downregulation of IL-19 and an upregulation of IL-10 mRNA levels in tumor cells compared to healthy control cells." (PMID 36045346, 2022). "Therefore, an increase in the amount of IFN-γ in tumor tissues leads to an increase in the number of immune suppressor cells, and the levels of effector molecules, such as IL-10 and TGF-β, secreted by these cells also increase." (PMID 36429033, 2022). "IL-10 produced by MDSCs induce Tregs and enhance immunosuppression at the tumor site." (PMID 35172851, 2022). "It is reported that CARD9 is highly expressed in the infiltrated macrophages during carcinoma progression with enhanced production of tumor-promoting cytokines (IL-10 and IL-1α), and decreased production of anti-tumor cytokine IL-12, thus, contributing to tumor metastasis." (PMID 35432375, 2022). "Additionally, we tested the CSF cytokine (e.g., IL-6, IL-10) levels in the tumor-bearing mice after Trojan bacteria injection." (PMID 36050316, 2022). "Finally, anti-IL-9 antibody immunotherapy resulted in suppression of tumor development even in established experimental NSCLC and was associated with reduced IL-10 production in the lung." (PMID 35514957, 2022). "This review discussed selected relevant soluble factors [transforming growth factor-beta (TGFβ), interleukin-6 (IL-6), IL-10, IL-23] and cellular components of the innate immunity, as drivers of tumor progression, immunosuppression, and angiogenesis within the PCa-TME." (PMID 36338516, 2022). "The role of B cells may be relevant in promoting the early stages of oncogenesis through their ability to produce IL-10 and IgG that activate the M2 pro-tumor phenotype of macrophages." (PMID 36361889, 2022). "Moreover, we have demonstrated that incorporating CD28 signaling in CAR MUC1 upregulated the immunosuppressive cytokines, IL-4 and IL-10, upon encountering the targeted tumor cells." (PMID 36457849, 2022). "In addition, IL-10 inhibits the induction of the tumor-specific T helper type 1 (Th1) cells, the production of IL-12 by macrophages and the antigen presentation." (PMID 35335881, 2022). "The data revealed that elevated levels of IFNα (∼25.62 pg/ml), IFNβ (∼38.71 pg/ml), TNFα (∼72.64 pg/ml), IL‐6 (∼139.26 pg/ml), IL‐12p40 (∼100.78 pg/ml), and IL‐10 (∼23.06 pg/ml) were detected in the tumours treated with 3p‐125b‐ASO‐loaded RBCEVs as compared to the controls." (PMID 35430766, 2022). "Consistently, loss of SHP-2 in BMDMs induces decreases in M1 macrophage-related gene expression (iNOS, IL-6, and TNF-α) and increases in M2 macrophage-related gene expression [Arg1, Fizz1, Ym-1, and IL-10] to promote M2 polarization of TAMs in the tumor microenvironment." (PMID 36380016, 2022).
tumor (continued). "The increased serum IL10 may originate from the tumor tissue where it was also upregulated in damp-heat syndrome." (PMID 35957897, 2022). "Although has traditionally been considered as pro-tumour cells, recently it has been demonstrated its anti-tumour function, as described in primary human prostate (IL-10 production is involved in angiogenesis inhibition), OSCC and CRC both by eosinophils infiltration)." (PMID 35406451, 2022). "Our group has found that within the protein sequence of nonmutated tumor associated antigens are Class II epitopes that selectively elicit either an IFN-γ or an IL-10 dominant response to antigen stimulation." (PMID 35948756, 2022). "Additionally, some IRGs with copy number amplification (HMGB1, IL17RA, and BAX) showed increased expression in tumor tissues, while some IRGs with copy number deletions (IL10, NT5E, and ENTPD1) showed decreased expression in tumor tissues." (PMID 36386817, 2022). "For instance, in hepatocellular carcinoma, while there are increased numbers of IL-10+ Bregs in the peripheral blood, which are indicative of the generation of a pro-tumour environment, there are also increased levels of IL-35, a cytokine that has recently been associated with Breg function." (PMID 35350071, 2022). "Pegylated IL-10 has been previously shown to improve tumor control." (PMID 35203357, 2022). "Th2 cells generate IL-4 and IL-10, which promote tumor growth by inhibiting the host immune system." (PMID 36204318, 2022). "Interestingly, cytokines produced by classical pro-tumor immune cells such as Tregs, which produce IL-10 and IL-35; Th17 cells, which produce IL-17 and IL-22; or Th2 cells with IL-4, are all pro-angiogenic factors." (PMID 35626056, 2022). "The cytokine IL10, which showed high expression in the high m5CrLS score, could inhibit the release of IL12A from dendritic cells, thus causing anti-tumor immunosuppressive effects." (PMID 35309316, 2022). "The M2 population may then release TGF-β and IL-10, with roles in inhibiting T cell anti-tumor immunity." (PMID 36497422, 2022). "However, only tumor stage (p = 0.000; HR = 1.329; 95% CI 1.151–1.534) and IL-10 (p = 0.005; HR = 4.1401; 95% CI 1.538–10.934) were independently associated with a shorter OS." (PMID 35255925, 2022). "Studies have shown that IL6 and IL10 can directly or indirectly stimulate NK cell activity, thus exerting anti-tumor effects, which is consistent with previous studies indicating that NK cells are highly expressed in LCC and significantly correlated with the prognosis of patients." (PMID 35936748, 2022). "Indeed, IL10 promotes the secretion of anti‐inflammatory factors in the body but also inhibits effector molecules to achieve tumour immunosuppression." (PMID 36433652, 2022). "However, a key cytokine, whose function further demonstrates the crucial roles of inflammation in sustaining tumor growth, is IL-10, which inhibits the inflammatory effects of IL-6 and IL-12/IL-23 and inhibits tumor-promoting inflammation." (PMID 35158821, 2022). "However, monocytes in the TME are influenced by tumor-derived cytokines (i.e., M-CSF, IL-10, IL-6, and TGF-β) and differentiate into tumor-promoting M2-type macrophages (i.e., tumor-associated macrophages, TAMs; Quail and Joyce, 2013)." (PMID 36408222, 2022). "Moreover, Bregs can dampen anti-tumor immunity and elicit tumor growth by interacting with cancer cells and producing IL-10." (PMID 36551635, 2022). "If cancer cells survive and rewire to express IL-10 production in the tumor microenvironment, it may mainly act as a potent cancer promoter." (PMID 36009467, 2022). "In CRC, we found that Anaerolineae and TM7—oral microbes that also inhabit the human gastrointestinal tract, and are known to promote oral and colorectal tumorigenesis—are negatively correlated with host genes enriched in the tumour-promoting interleukin-10 signalling pathway, such CXCL8 and IL1RN." (PMID 35577971, 2022).
tumor (continued). "Binding to its cognate ligand CD275 (ICOSL, ICOS ligand), another B 7 family member, which is apparent on DCs, B cells, several non-immune cells and tumor cells, caused Treg expansion, IL-10 release by activated T cells and attenuated B-cell activation." (PMID 35406483, 2022). "However, Th2 cells release the cytokines IL-4, IL-6, IL-10, and IL-13, which stimulate M2 TAMs, inducing tumor promotion and downregulating antitumor immunity." (PMID 36380016, 2022). "Therefore, Breg cells promoted the survival of tumor cells by expressing high IL-10 and TGF-β to suspend anti-tumor immunity." (PMID 35563678, 2022). "IFN- γ production reduced from B cell-knock out splenic cells when cocultured with WT B cells, and IL-10 production from B cells increased after coculturing with irradiated melanoma cells, not sarcoma cells, indicating that Breg cells suppress the anti-tumor immunity to certain tumors." (PMID 36033455, 2022). "Research from other tumor types suggests that EMT progression is mediated by immune regulation; specifically, cytokines such as TGF-beta, IL-10, and immune cell populations such as tumor-associated macrophages and some subsets of CD4+ and CD8+ T cells appear to be critical to this regulation." (PMID 36139624, 2022). "Additionally, targeting complement/C3aR/C5aR/IL-10 pathway has been suggested to synergize other treatment modalities, as it enhances the T-cell anti-tumor efficacy." (PMID 35173724, 2022). "As an anti-inflammatory factor, IL-10 at a high concentration may also play a role in immune tolerance and, thus, act as a tumor suppressor." (PMID 35893303, 2022). "In a multi-variant analysis, IgG4 positivity (p = 0.001; HR = 3.366; 95% CI 1.607–7.050), tumor IL-10 (p = 0.000; HR = 7.195; 95% CI 2.418–21.411) and tumor stage and tumor stage (p = 0.000; HR = 1.442; 95% CI 1.0247–1.667) were independently associated with a shorter RFS." (PMID 35255925, 2022). "Intriguingly, some studies illustrated that a half-life-extended IL-10–Fc can expand terminally exhausted CD8+ tumor-infiltrating lymphocytes (TILs) directly, which means IL-10 may function positively in the anti-tumor process." (PMID 36568190, 2022). "Tumor-infiltrating mast cells impair antitumor immunity, partly by secreting IL-10 and TGF-β." (PMID 36233088, 2022). "In addition, tumor cell-released autophagosomes (TRAPs) converted macrophages to an immunosuppressive M2-like phenotype that is defined by PD-L1 and IL-10 expression, resulting in T cell inactivation and cold TME formation." (PMID 36300110, 2022). "Similarly, IL-10, a common anti-inflammatory factor, played a dual role as a pro-oncogenic factor as well as a tumor suppressor in cervical cancer." (PMID 36371539, 2022). "Moreover, IL-10-producing B cells are also being found to promote tumor growth in non-Hodgkin B cell lymphoma." (PMID 36033455, 2022). "Studies targeting TAMs have found that CuNG (a copper chelate) can promote reprogramming of TAMs, promote the secretion of IL-12 and reduce the secretion of TGF-β and IL-10, thus altering their immunosuppressive properties and reactivating the immune response of T cells against tumor cells." (PMID 36419894, 2022). "We then analyzed the associations between CXCL2 expression and classical macrophage phenotype markers of M0 (undifferentiated) (AIF1), M1 (anti-tumor) (IL12A, TNF, NOS2, PTGS2) and M2 (tumor-promoting) (IL10, CD163, TGFB1, CSF1R) in TCGA-LIHC cohort with Spearman’s rank correlation test." (PMID 36276119, 2022). "IL-10 is a cytokine that has both anti-inflammatory and pro-tumor/anti-tumor effects." (PMID 36091125, 2022). "In the tumor-free adipose matrix, the microenvironment, by secreting soluble factors, stimulates the increase in the expression of inflammatory genes and the decrease in the secretion of anti-inflammatory IL-10." (PMID 35205204, 2022). "Normal and tumor cells released low levels of IL-1β and IL-10." (PMID 35335367, 2022).